KIF3A (kinesin family member 3A)
Description:
Microtubule-based anterograde translocator for membranous organelles, such as primary cilium and centriole. Shows a plus end-directed microtubule sliding activity in vitro. Plays a role in primary cilia formation, probably by mediating transport of proteins into primary cilia. Mediates smoothened (SMO) translocation into primary cilia in response to hedgehog morphogens. Plays a role in centriole cohesion and subdistal appendage organization and function. Regulates the formation of the subdistal appendage via recruitment of DCTN1 to the centriole. Also required for ciliary basal feet formation and microtubule anchoring to mother centriole.
Synonyms: FLA10; KLP-20
Tractability: PROTAC: ubiquitination databases record sites on it; its protein half-life has been measured.
Target class: Other cytosolic protein
Gene: Protein-coding gene on chromosome 5 (132,692,628 to 132,737,638, reverse strand). Ensembl gene ENSG00000131437.
Subcellular location: Cytoplasm, cytoskeleton; Cell projection, cilium; Cytoplasm, cytoskeleton, microtubule organizing center, centrosome, centriole
Subcellular location (Human Protein Atlas): Basal body; Cytosol; Nucleoplasm; Primary cilium
Pathways (Reactome):
Signal Transduction: Activation of SMO; Hedgehog 'off' state
Vesicle-mediated transport: COPI-dependent Golgi-to-ER retrograde traffic; Translocation of SLC2A4 (GLUT4) to the plasma membrane
Hemostasis: Kinesins
Immune System: MHC class II antigen presentation
Organelle biogenesis and maintenance: Intraflagellar transport
Gene Ontology:
Molecular function: protein binding; protein phosphatase binding; small GTPase binding; spectrin binding; microtubule motor activity; plus-end-directed microtubule motor activity; ATP binding; cytoskeletal protein binding; microtubule binding; protein-containing complex binding
Biological process: protein localization to cell junction; protein transport; anterograde axonal transport; centriole-centriole cohesion; cilium assembly; microtubule anchoring at centrosome; organelle organization; plus-end-directed vesicle transport along microtubule; positive regulation of smoothened signaling pathway; protein localization to non-motile cilium; microtubule-based movement; transport along microtubule
Cellular component: centriole; centrosome; extracellular exosome; kinesin II complex; microtubule cytoskeleton; spindle microtubule; ciliary tip; cilium; cytosol; kinesin complex; non-motile cilium; axon cytoplasm; cytoskeleton
Genetic constraint (gnomAD): Loss-of-function variants: 11 observed, 60.87 expected, observed/expected ratio (o/e) 0.18, 90% interval 0.11 to 0.3. The upper end of that interval is the gene's LOEUF score, 0.3, which puts it in group 1 of 6, group 1 being the genes least tolerant of losing a copy. Missense variants: 434 observed, 701.88 expected, observed/expected ratio (o/e) 0.62, 90% interval 0.57 to 0.67. Synonymous variants: 198 observed, 225.24 expected, observed/expected ratio (o/e) 0.88, 90% interval 0.78 to 0.99.
Homologues: Orthologues: chimpanzee KIF3A (100% identical), macaque KIF3A (99% identical), dog KIF3A (99% identical), rabbit KIF3A (99% identical), pig KIF3A (98% identical), guinea pig KIF3A (98% identical), mouse Kif3a (98% identical), chimpanzee KIF3A (96% identical), rat Kif3a (93% identical), tropical clawed frog kif3a (92% identical), zebrafish kif3a (89% identical), Drosophila melanogaster Klp64D (55% identical), and 1 more. Paralogues in human: KIF3B (48% identical), KIF3C (44% identical), KIF17 (42% identical), KIF13B (30% identical), KIF13A (30% identical), KIF1B (29% identical), KIF11 (29% identical), KIF16B (29% identical), KIF1A (29% identical), KIF15 (27% identical), KIF21A (27% identical), KIF21B (27% identical), and 29 more.
Diseases named in the same sentence as KIF3A in open-access papers:
KIF3A is named in the same sentence as 72 diseases in open-access papers, as found by Europe PMC text mining. Sharing a sentence is not in itself a finding about the gene and the disease. The quoted sentences say what the papers report.
asthma (13 papers, 2011 to 2025). "The kinesin family number 3A (Kif3a) is a subunit of the kinesin‐2 motor protein that regulates microtubule function and trafficking, which is one of the susceptibility sites of asthma." (PMID 39949885, 2025). "Kif3a is not only a susceptibility gene locus associated with asthma but also an important kinesin required for ciliogenesis that is known to transduce key extracellular signals, including the sonic hedgehog (SHH) pathway." (PMID 39949885, 2025). "Additional genetic factors, such as genetic variations in some PCD-causing genes (DNAH14, DNAAF3, DNAH6, DNAH5, KIFC2, KIF3A), are associated with the increased risk of asthma development." (PMID 39337527, 2024). "The Greater Cincinnati Pediatric Clinic Repository (GCPCR) found a relationship between a dependent genetic variant family member Kinesin 3A (KIF3A) with AD-asthma comorbidity in a population cohort." (PMID 35455494, 2022). "KIF3A SNPs rs11740584 and rs2299007 have been associated with asthma and AD7, and both are CpG SNPs, such that the alternate or non-reference allele creates a new CpG site." (PMID 32796837, 2020). "Genetic variation in the cilia structural gene kinesin family number 3A (KIF3A) has been associated with AD, asthma, and the atopic march by numerous studies." (PMID 32796837, 2020). "Other proteins predicted to be related to multimorbidity are KIF3A, already known to be associated to asthma, eczema and the atopic march, and predicted to be implicated also in rhinitis." (PMID 28598986, 2017). "We found that seven of nine KIF3A SNPs genotyped were significantly associated with asthma in our discovery Caucasian population and in independent Caucasian and African American populations – all from Cincinnati." (PMID 21912604, 2011). "The most strongly associated gene, KIF3A, was first reported by our group as having a role in asthma in 2009." (PMID 21912604, 2011). "Our analysis revealed all 7 previously associated KIF3A SNPs (as well as several other imputed SNPs) were significantly associated with asthma in this population (p-value≤0.01)." (PMID 21912604, 2011). "Using this approach, we have identified KIF3A as a possible susceptibility gene for childhood asthma and allergic disease." (PMID 21912604, 2011). "Our data indicate that KIF3A rs7737031 (T-allele) has an asthma population attributable risk of 18.5%." (PMID 21912604, 2011). "The association between KIF3A rs7737031 and asthma was validated in 3 independent populations, further substantiating the validity of our gene selection approach." (PMID 21912604, 2011). "We found that ADCY2, PDE4B, DNAH5 and KIF3A were again associated with asthma (p<0.05) at the gene level." (PMID 21912604, 2011). "While KIF3A genetic associations with asthma and AD have been replicated, the mechanism underlying this susceptibility is unknown." (PMID 32796837, 2020). "Our analysis revealed that all seven of the asthma-associated KIF3A SNPs had FST values≥0.32, while the remaining 2 SNPs had much lower FST estimates, suggesting that FST may be useful in identifying those SNPs most likely to be associated with asthma." (PMID 21912604, 2011). "Notably, seven of nine KIF3A SNPs were associated with asthma with more than a 2-fold increase in the odds ratio for asthma (p<10−4) even after applying an LD adjusted Bonferroni correction for 160 pairwise comparisons with 0.13 correlation (α = 6×10−4)." (PMID 21912604, 2011). "KIF3A has also been associated with aspirin sensitive asthma." (PMID 21912604, 2011). "The observed association was strongest for KIF3A rs7737031 which had a PAR for asthma of >18%." (PMID 21912604, 2011). "Considering that a large number of studies have reported that miRNAs exhibited a crucial role in asthma; for example, miR-145-5p promoted asthma pathogenesis by inhibiting kinesin family member 3A expression in mouse airway epithelial cells (AECs)." (PMID 39867638, 2025).
asthma (continued). "In the next step, we will study the regulatory effect of M. Chamomile on autophagy by knocking down or overexpressing KIF3A levels in cellular and animal asthma models." (PMID 39949885, 2025). "Previously, we found that M. chamomile had an anti‐asthma effect through the target protein Kif3a using proteomic technology." (PMID 39949885, 2025). "In vitro, knocking down Kif3a increased epithelial apoptosis, boosted CCL17, IL‐5, and IL‐8 transcription, and raised COX‐2 protein levels and β‐catenin translocation; Conversely, Kif3a overexpression greatly alleviates asthma." (PMID 39949885, 2025). "Kinesin family member 3A (Kif3a), a subunit of heterotrimeric kinesin 2, regulates microtubule function and transport, which plays an important role in the pathogenesis of asthma." (PMID 39949885, 2025). "One study has shown that the expression of PCD-related genes, DNAH5, KIFC2 and KIF3A, are downregulated in asthma, and that SNPs in these genes correlate with asthma and disease severity." (PMID 39337527, 2024). "Intranasal administration of miR-145–5p antagomir to mice reversed HDM-induced decrease in KIF3A (expressed in airway epithelial cells), reduced inflammatory response in the lung, and ultimately, modulated asthma phenotypes." (PMID 36203653, 2022). "For example, miR-145-5p exacerbated asthma pathogenesis through suppressing KIF3A expression in mouse airway epithelial cells." (PMID 32065213, 2020). "Here, we verify that KIF3A is a novel candidate gene for childhood asthma and show that its expression is down regulated in nasal epithelial cells in asthmatics." (PMID 21912604, 2011). "As an additional independent validation of our results, we also measured expression of KIF3A in lung RNA isolated from a house dust mite-induced murine asthma model." (PMID 21912604, 2011). "The effect of M. Chamomile on improving asthma inflammation through KIF3A and autophagy will be further clarified, providing a theoretical basis for the clinical development and application of M. Chamomile in the treatment of asthma." (PMID 39949885, 2025). "M. Chamomile, as a potential autophagy inhibitor, could inhibit over‐activated autophagy levels, increase Kif3a expression, and decrease apoptosis to ameliorate asthma." (PMID 39949885, 2025). "In a recent human study, the KIF3A rs12186803 risk allele differentially interacts with the sensitization pattern to modify asthma risk, resulting in a high risk of asthma even without clinical eczema." (PMID 35455494, 2022). "Our investigation revealed that six of these genes (PDE4B, SPRR2B, ADCY2, KIF3A, DNAH5, and PLAU) were located in chromosomal regions that had been previously linked to asthma or other allergic disease phenotypes and had been shown to be regulated during allergic inflammation." (PMID 21912604, 2011). "Importantly, we observed that 7 of 9 SNPs in the KIF3A gene more than doubled the odds of asthma (OR = 2.3, p<0.0001) and increased the odds of allergic disease (OR = 1.8, p<0.008)." (PMID 21912604, 2011). "Alternatively, diminished KIF3A expression may contribute to the lungs' inability to clear mucus and remove inhaled particles and aeroallergens therefore exacerbating the asthma and/or allergic phenotypes." (PMID 21912604, 2011). "SNPs in KIF3A were also to a lesser degree, associated with other allergic diseases independent of asthma demonstrating the importance of appropriate phenotyping and selection of controls in genetic studies of asthma." (PMID 21912604, 2011). "Hence, MC is a potential autophagy inhibitor, which could up‐regulate the level of Kif3a and down‐regulate the level of Caspase‐3 through inhibiting the level of excessive activation of autophagy to exert an anti‐asthma effect." (PMID 39949885, 2025). "Hence, MC could play an anti‐asthma role by up‐regulating Kif3a level, inhibiting autophagy, and apoptosis." (PMID 39949885, 2025).
asthma (continued). "Hence, MC is a potential autophagy inhibitor, which could inhibit over‐activated autophagy levels to enhance Kif3a expression, thereby decreasing apoptosis to against asthma." (PMID 39949885, 2025). "To further support our findings, we directly genotyped KIF3A rs7737031, the SNP with the most significant association in our discovery population, and again observed a significant association with asthma in the Puerto Rican (p-value = 0.0458), but not the Mexican trios (p-value = 0.471)." (PMID 21912604, 2011). "Another study with a mouse model of asthma induced by HDM found an up-regulation of miR-145-5p expression and a down-regulation of kinesin Family Member 3A (KIF3A) in airway epithelial cells." (PMID 38337625, 2024). "Regardless of the mechanism of action, KIF3A is clearly down-regulated in asthma, supporting a role for this novel gene in the pathogenesis of this disease." (PMID 21912604, 2011). "The four loci originally discovered through GWAS on eczema (FLG, IL4/KIF3A, OVOL1 and C11orf30/LRRC32) did not reveal an effect on asthma alone." (PMID 26542096, 2015).
cyst (12 papers, 2015 to 2025). A sac-like closed membranous structure that may be empty or contain fluid or amorphous material. "Conditional deletion of Kif3a in renal epithelial cells using tissue-specific promoters like Pax8-Cre or Ksp-Cre causes loss of cilia and rapid cyst formation." (PMID 40801635, 2025). "The crucial role of the cilium in regulating pancreas homeostasis has been clearly demonstrated with the pancreas-specific Kinesin Family Member 3A (Kif3a) knock-out mice, which are characterized by the loss of cilia and present severe abnormalities and cyst formation within the pancreas." (PMID 32053947, 2020). "Consistent with our observation, inactivation of the intraflagellar transport genes Kif3a and Ift20 led to the loss of cilia, aberrant OCD, and cyst formation." (PMID 36627370, 2023). "We investigated the flow-dependent PT transport in 3 major polycystic kidney disease (PKD) and ciliopathy animal models of Pkd1-, Pkd2-, and Kif3a-KO mice after gene KO but prior to cyst formation." (PMID 33886508, 2021). "Specific pancreatic inactivation of kinesin family member 3a (Kif3a), a molecular motor used to build the cilia during development, led to cyst formation and duct enlargement." (PMID 30048442, 2018). "Interestingly, simultaneous knockout of both Pkd1 and Kif3a reduces cyst severity compared to Pkd1 deletion alone." (PMID 40801635, 2025). "In ARPKD kidney organoids, overexpressing autophagy-related 5 (ATG5) or knocking out the primary cilia-associated gene kinesin family member 3 A (KIF3A) activates autophagy and suppresses cyst formation, with cilia ablation accompanied by upregulated autophagy." (PMID 41359105, 2025). "Since miR-17 inhibition slows cyst growth in ciliopathy models (Kif3a-KO and Nphp3pcy/pcy), the beneficial effects of anti-miR-17 treatment may also be observed in other forms of cystic kidney disease besides ADPKD." (PMID 28205547, 2017). "The miR-17 miRNA family aggravates cyst growth in the Kif3a-KO ciliopathy model of PKD12." (PMID 28205547, 2017). "In the case of Pkd1 or Kif3a mice, there was no abnormality in flow-dependent regulation of PT transport, and SCH23390 had no salutary effect on cyst formation." (PMID 33886508, 2021).
ciliopathy (10 papers, 2015 to 2024). A genetic disorder of the cellular cilia or the cilia anchoring structures, the basal bodies, or of ciliary function. "To examine the role of Kif3a in tissues contributing to the craniofacial complex we conditionally excised Kif3a using each of the three drivers detailed above and examined craniofacial domains frequently affected in ciliopathies." (PMID 28346501, 2017). "Further studies are required to address how CAPK phosphorylation of KIF3A-Thr672 affects IFT and ciliogenesis, and whether deregulation of this phosphorylation event is required for the ciliopathy phenotypes caused by CAPK dysfunction." (PMID 31277411, 2019). "Individuals with ciliopathies resulting from defects of the primary cilia often have CLP, and tissue-specific deletion of the intraflagellar transport genes intraflagellar transport 88 (Ift88) or kinesin family member 3A (Kif3a) in mice causes CLP." (PMID 30760477, 2019). "We have previously shown that miR-17∼92 inhibits PKD1 and PKD2 and aggravates disease progression in a non-orthologous ciliopathy (Kif3a-KO) model of cystic kidney disease." (PMID 28205547, 2017).
Renal cyst (8 papers, 2010 to 2022). A fluid filled sac in the kidney. "Although some of the defects, such as cardiac looping, holoprosencephaly, polydactyly, and cystic kidney are common in major ciliary gene mutations, such as Kif3a or Ift88, the phenotypic spectrums of the mouse models for DAP genes are diverse." (PMID 36407107, 2022). "Mice with double mutations in Pkd1 and Kif3a or in Pkd2 and Ift20 exhibited an intermediate phenotype between the milder cilia-induced and more severe polycystin-induced cystic kidneys." (PMID 35253003, 2022). "Mice with mutations in ciliary assembly genes (Kif3a, Ift88, Ift140, Ift20) develop renal cysts." (PMID 35253003, 2022). "Additional supporting evidence implicating Kif12 as the Mpkd2 modifier gene candidate is provided by recent studies that demonstrate renal cystic disease-attenuating effects of Kif3a deletion in Pkd1 and Pkd2 mouse models." (PMID 26295839, 2015). "Cilia proteins KIF3A, IFT88 and IFT20, which are involved in IFT, are required for renal ciliogenesis; inactivation of each is known to cause cystic kidney disease." (PMID 23762375, 2013). "We observed no morphological changes of the kidneys from the Pkd1-, Pkd2-, and the Kif3a-KO mice 2 weeks after the induction (at the age of 8 weeks) and observed some dilated kidney tubules after 5 weeks of induction; renal cysts developed from 8 weeks of induction in Pkd1 and Pkd2 KO mice." (PMID 33886508, 2021). "In addition, neither single Pkd1 and Kif3a nor double Pkd1 and Kif3a mutant mice developed polycystic kidney disease, unlike the reported additive effects of Pkd1 and Pkd2 deficiency to enhance renal cyst formation." (PMID 21151991, 2010).